WNT5A (Wnt family member 5A)
Diseases named in the same sentence as WNT5A in open-access papers (continued):
Sharing a sentence is not in itself a finding about the gene and the disease.
breast carcinoma (continued). "One study of breast cancer reports an increase in expression of Wnt5a/b and their respective receptors Ror1 and 2 in brain metastases." (PMID 29765514, 2018). "A schematic diagram shows the most important WNT5A-triggered signaling pathways believed to participate in the regulation of breast cancer cell migration and invasion." (PMID 30171384, 2018). "We believe that the effect on β-catenin signaling is a major deciding factor that governs the WNT5A response in breast cancer cells." (PMID 30171384, 2018). "DNA microarray analysis revealed that ALCAM expression in Wnt5a-positive breast cancer cells is induced by Wnt5a." (PMID 29765514, 2018). "In the present review, we will discuss how WNT5A has emerged as a tumor suppressor in breast cancer, and how re-activating its signaling pathway in breast cancer cells can be an attractive alternative to curb this dreaded disease." (PMID 30171384, 2018). "HuR was shown to block Wnt5a signaling in human breast cancer by direct inhibition of translation, whereas in the intestinal epithelium HuR supports Wnt signaling by stabilizing LRP6 mRNA." (PMID 29364956, 2018). "Recently, it was shown that in breast cancer Wnt5a inhibits proliferation of tumour-initiating cells via TGFβ/SMAD signaling." (PMID 29453334, 2018). "The present review focuses on the relevance, mechanisms, and therapeutic potential of targeting WNT5A as a future anti-metastatic treatment strategy for breast cancer patients by restoring WNT5A signaling as an innovative therapeutic option." (PMID 30171384, 2018). "In breast cancer patients, WNT5A protein expression has been observed to be significantly reduced in between 45 and 75% of the cases and associated with early relapse and reduced disease-free survival." (PMID 30171384, 2018). "The migratory capacity of ER-positive breast cancer cells increased with constitutive expression of Wnt5a and decreased with Wnt5a knockdown." (PMID 29765514, 2018). "In previous studies, the inclusion of all subtypes, with their remarkably distinct prognoses, likely interfered with the accurate determination of the role of Wnt5a in breast cancer." (PMID 29765514, 2018). "We investigate the mechanism of malignant transformation in breast cancer by Wnt5a through biological analyses of cultured cells." (PMID 29765514, 2018). "Considering all these reports, it is certain that WNT5A signaling exerts tumor-suppressive effects in breast cancer." (PMID 30171384, 2018). "In breast cancer, reconstitution of WNT5A signaling inhibits crucial components of aerobic glycolysis that result in decreased lactate production and uptake suggest that a loss of WNT5A expression might be involved in a metabolic shift to glycolysis during early breast cancer development." (PMID 30171384, 2018). "Somewhat surprisingly, it was shown that WNT5A signaling impairs breast cancer migration via activation of Cdc42." (PMID 30171384, 2018). "As Wnt5a is reported to associate with cell migration, we conducted cell migration assays to determine the migratory capacity of Wnt5a-positive breast cancer cells." (PMID 29765514, 2018). "Text mining of PubMed literature with an R package RISmed revealed that most of them are with unclear roles in breast cancer except for Igfbp3, Mmp14, Fap, Timp3 and Wnt5a." (PMID 29615825, 2018). "Our results demonstrate that C10 inhibits TLR3 and Wnt5a mRNA expression in MCF-7 breast cancer cells." (PMID 29371911, 2017). "Studies on the role of Wnt5a in breast cancer reported contradicting evidence, with Wnt5a either enhancing or suppressing invasiveness of different breast cancer cells." (PMID 28695110, 2017). "WNT5A signaling inhibits aerobic glycolysis in breast cancer cells via a β-catenin-PFKP axis resulting in reduced lactate production." (PMID 29069720, 2017).
breast carcinoma (continued). "While WNT5A is considered to have a tumor-suppressive function in colon cancer, neuroblastoma, breast carcinomas, and leukemia, it has also been shown to promote progression of gastric cancer, melanoma, lung and pancreatic cancer." (PMID 28886116, 2017). "To study the effects of extracellular lactate on breast cancer cell migration in the absence and presence of WNT5A signaling, we treated breast cancer cells with sodium L-lactate (10 mM) under different conditions and evaluated their migratory responses." (PMID 29069720, 2017). "In the current study, we investigated the role of WNT5A signaling in the regulation of aerobic glycolysis in breast cancer." (PMID 29069720, 2017). "In breast cancer, for example, WNT5A is known to inhibit cell migration and invasion partly by reducing the levels of CD44." (PMID 28886116, 2017). "WNT5A expression significantly reduced PFKP expression in both breast cancer cell lines (i.e., MDA-MB-468-5A and MDA-MB-231-5A) compared to their respective EV-transfected control cells." (PMID 29069720, 2017). "In the present study, we performed a more thorough investigation of the role of WNT5A signaling on aerobic glycolysis in breast cancer cells using several different approaches." (PMID 29069720, 2017). "It has also been shown that WNT5A impairs breast cancer cells invasion partly by reducing MMP9 activity." (PMID 28886116, 2017). "Since WNT5A inhibits breast cancer cell migration and invasion in part by reducing the levels of CD44, we have explored if WNT5A signaling regulates the expression of this protein also in prostate cancer tissue." (PMID 28886116, 2017). "Morphologically, WNT5A expressing breast cancer cells exhibited less migration relevant membrane protrusions, as compared to control EV transfected cells." (PMID 29069720, 2017). "On the basis of our results, we have provided a schematic diagram on how WNT5A signaling regulates aerobic glycolysis and thereby cell migration in breast cancer cells." (PMID 29069720, 2017). "That WNT5A signaling inhibits endogenous migration of breast cancer cells, we next investigated if active WNT5A signaling in breast cancer cells can counteract the effect of extracellular lactate." (PMID 29069720, 2017). "The down-regulation of PFKP, a key glycolytic enzyme, by WNT5A signaling correlates with the ability of WNT5A to decrease lactate secretion in breast cancer cells." (PMID 29069720, 2017). "Both breast cancer cell lines expressing the WNT5A plasmid (MDA-MB-468-5A and MDA-MB-231-5A) showed significant decreases in lactate production after 72 h compared to the respective empty vector (EV)-transfected control cells." (PMID 29069720, 2017). "For these experiments, we used an anti-active-β-catenin antibody and found that WNT5A signaling significantly reduced the amount of active-β-catenin protein in breast cancer cells." (PMID 29069720, 2017). "Wnt5a promotes breast cancer cell migration via Dishevelled 2 (Dvl2)/Dishevelled-associated activator of morphogenesis 1 (Daam1)/RhoA signaling pathway." (PMID 28289332, 2017). "Recent studies have highlighted the important pathologic role of TLR3 and Wnt5a in progression, sustenance and metastasis of breast cancer." (PMID 29371911, 2017). "Compared to their respective controls (EV), migration was significantly decreased in WNT5A-expressing breast cancer cells." (PMID 29069720, 2017). "In conclusion, in this study we explored effects of Wnt5a and Ror2 perturbations in the ER-positive breast cancer cell line MCF-7 on the phenotypic and gene expression levels." (PMID 28695110, 2017). "We also stimulated the breast cancer cells lines with recombinant WNT5A (rWNT5A) and Foxy5, a WNT5A-mimic peptide that is presently in a clinical phase 1b study." (PMID 29069720, 2017). "We first transfected both breast cancer cell lines with a WNT5A plasmid to study the long-term effects of WNT5A signaling in an environment that mimics in vivo conditions." (PMID 29069720, 2017).
breast carcinoma (continued). "Here we investigated the impact of WNT5A signaling on aerobic glycolysis and evaluated its effects on breast cancer cell migration/invasion." (PMID 29069720, 2017). "The rationale behind this is that WNT5A signaling is known to impair invasion of breast cancer cells in part by reducing extracellular MMP9 activity." (PMID 28886116, 2017). "Significant reductions in the expression of active β-catenin were observed in the cell lysates of both WNT5A-expressing breast cancer cell lines as compared to their respective control EV cells." (PMID 29069720, 2017). "Overall, our results demonstrate that the WNT5A-mediated reduction in CD44-AKT signaling plays an important role in inhibiting breast cancer cell migration and invasion." (PMID 27623766, 2016). "Foxy5 is a WNT5A derived N-formylated hexapeptide which mimics tumor suppressive effects of WNT5A on breast cancer both in vitro and in vivo." (PMID 26514730, 2016). "Here, we demonstrate that Wnt5a represses rRNA synthesis in breast cancer cells by promoting nucleolar localization of DVL1 and its subsequent association with rDNA chromatin." (PMID 27500936, 2016). "Some particles from breast cancer cells were responsible for the upregulation of Wnt5a in macrophages." (PMID 27608847, 2016). "We previously reported that WNT5A at least in part inhibits the migration and invasion of breast cancer cells by reducing the production and secretion of MMP9." (PMID 27623766, 2016). "This study demonstrated that WNT5A inhibits CD44 expression and its downstream AKT signaling, which further explains how WNT5A signaling impairs breast cancer cell migration and invasion." (PMID 27623766, 2016). "WNT5A was transiently knocked down using specific siRNAs, whereas WNT5A signaling was induced in MDA-MB468 and MDA-MB231 breast cancer cells by stably transfecting cells with WNT5A or treating them with recombinant WNT5A (rWNT5A)." (PMID 27623766, 2016). "While the pro-cell migratory effects of WNT-5A in breast cancer require further studies, it is quite possible that WNT-5A regulates breast cancer metastasis depending on the tumor-microenvironment communication." (PMID 26514730, 2016). "Based on these results, we postulated that suppression of breast cancer cell migration and invasion by WNT5A is due to EMT reversal." (PMID 27623766, 2016). "Unlike in mammary epithelial cells, the inhibition of migration and invasion by WNT5A signaling is an EMT-independent event in breast cancer cells." (PMID 27623766, 2016). "We therefore assayed rDNA transcription after treatment with recombinant Wnt5a protein by measuring the levels of 47S pre-rRNA, using human estrogen receptor positive (ER+) breast cancer cells (MCF7)." (PMID 27500936, 2016). "Subsequently, we validated our findings by Western blotting, demonstrating that WNT5A expression does indeed inhibit the expression of CD44 protein in WNT5A-expressing breast cancer cell lines." (PMID 27623766, 2016). "Other studies of breast cancer cells involving the treatment of cells with either recombinant WNT5A (rWNT5A) or the stable transfection of WNT5A protein demonstrated that breast cancer cell adhesion increased, whereas their migration decreased." (PMID 27623766, 2016). "Conversely, macrophage-derived Wnt5a promoted breast cancer cell invasiveness and gastric cancer cell migration." (PMID 27608847, 2016). "In contrast to the tumor-suppressor function of WNT-5A in breast cancer, studies have also suggested a cell migration-promoting role for WNT-5A." (PMID 26514730, 2016). "Here, we show that Wnt5a rapidly represses rDNA gene transcription in breast cancer cells and generates a chromatin state with reduced transcription of rDNA by RNA polymerase I (Pol I)." (PMID 27500936, 2016). "We observed a dose-dependent decrease in the expression of pAKT, thereby validating our finding that WNT5A indeed inhibits the CD44-AKT signaling pathway in breast cancer cells." (PMID 27623766, 2016).
breast carcinoma (continued). "Because CD44 overexpression alone is sufficient to induce breast cancer cell migration and invasion, we investigated the ability of WNT5A signaling to directly regulate CD44 expression in breast cancer cells." (PMID 27623766, 2016). "Altogether, we provide compelling evidence that, in breast cancer cells, WNT5A–VANGL2 signalling requires the integrity of the VANGL2–p62/SQSTM1 complex to associate with and phosphorylate JNK." (PMID 26754771, 2016). "The data from different research groups have revealed that WNT5A expression in clinical breast cancer samples is marker of good prognosis, whereas CD44 expression has been associated with poor prognosis." (PMID 27623766, 2016). "In contrast, breast cancer patient tissue microarrays revealed a strong correlation between the expression of Wnt5a in malignant epithelial cells and the frequency of CD163+ anti-inflammatory tumor-associated macrophages." (PMID 27571105, 2016). "It leads to reduction in the number of tumor-initiating cells and attenuates breast cancer growth in vivo suggesting that epigenetic silencing of WNT-5A via PIAS1 is an important feature in breast cancer." (PMID 26514730, 2016). "In contrast, Wnt5a enhanced mitochondrial-mediated oxidative phosphorylation respiration in breast cancer cells." (PMID 27571105, 2016). "In the present study, we showed that WNT5A affects breast cancer cell migration and invasion by inhibiting CD44 expression and downstream AKT signaling." (PMID 27623766, 2016). "For example, Wnt7a and Frizzled-9- (Fzd9-) mediated noncanonical Wnt signaling showed an antitumor activity, but Wnt5a exhibited contradictory effects on breast cancer." (PMID 27895670, 2016). "We found a significant reduction in the expression of pAKT in both WNT5A-transfected breast cancer cell lines (MDA-MB468-5A and MDA-MB231-5A) compared to control cells." (PMID 27623766, 2016). "The results obtained in breast cancer cells and in Xenopus show the existence of an evolutionarily conserved WNT5A–VANGL2–p62/SQSTM1–JNK signalling pathway." (PMID 26754771, 2016). "Wnt5a-induced accumulation of DVL1 in the nucleolus directly interferes with the synthesis of rRNA, suggesting that a tumor suppressive effect of Wnt5a in breast cancer cells is mediated by DVL1-dependent repression of rRNA synthesis." (PMID 27500936, 2016). "In breast cancer, Wnt5a signaling has been shown to exert tumor suppressive effects and loss of Wnt5a expression has been associated with accelerated tumor growth." (PMID 27500936, 2016). "As previously reported, Wnt5a-null mammary tumors exhibited increased Ki-67 expression levels compared to those derived from MMTV-PyMT/Wnt5a+/+ mice." (PMID 27500936, 2016). "We substantiated this conclusion by showing that Wnt5a-null mammary tumor cells display enlarged nucleoli, increased proliferation and increased SIRT7 expression in vivo." (PMID 27500936, 2016). "This provides a novel mechanism for how Wnt5a exerts tumor suppressive effects and why disruption of Wnt5a signaling enhances mammary tumor growth in vivo." (PMID 27500936, 2016). "It was recently shown that breast cancer CD163+ TAMs correlate with Wnt5a expression, the latter factor being responsible for macrophage reprogramming to an anti-inflammatory M2 status." (PMID 26243145, 2015). "In cellular and animal models of hematopoietic malignancies, colorectal cancer, thyroid carcinoma, and breast cancer, WNT5A has been shown to inhibit tumor cell proliferation and invasion." (PMID 25823923, 2015). "Our findings are consistent with a recent report that WNT5A can promote the stem cell-like properties of breast cancer cells." (PMID 25823923, 2015). "Our findings are consistent with the findings in breast cancer, in which a positive feedback loop has also been reported between WNT5A and PKC activation." (PMID 25823923, 2015).
breast carcinoma (continued). "In the context of breast cancer, Wnt5a induces invasiveness of cancer cells and the production of matrix metalloproteinase-7 and tumor necrosis factor-α in macrophages." (PMID 24944588, 2014). "In vitro experiments that co-cultured MCF-7 breast cancer cells and macrophages resulted in the upregulation of Wnt5a in the macrophages." (PMID 24944588, 2014). "Wnt5a appears to promote malignant progression in breast cancer in a microenvironment-dependent manner." (PMID 24944588, 2014). "Jöhnsson and Andersson transfected non-WNT5A expressing MCF-7 breast cancer cells with a mammalian vector carrying WNT5A cDNA." (PMID 24944588, 2014). "The exogenous administration of recombinant WNT5A protein to MDA-MB231 breast cancer cells suppressed mammosphere." (PMID 24586797, 2014). "Rac1 is reported to be essential for Wnt-driven expansion and transformation of intestinal stem cells and Wnt5a promotes breast cancer cell migration via the Dvl2/Rab35/Rac1 signaling pathway." (PMID 24962779, 2014). "In spite of the relative small number of paired breast tumor samples analyzed, the results supports that Wnt5A activation is involved in chemoresistance of breast cancer, consistent of the in vitro data." (PMID 25401518, 2014). "Collectively, these data support a model in which Wnt5a inhibits tumor formation and redirects mammary tumor phenotype in MMTV-Wnt1 tumors." (PMID 25401739, 2014). "To further examine the effects of WNT5A on gene expression and transcript processing in the highly metastatic breast cancer cell lines, we performed RNA-seq analysis with the same RNA used in the microarray assay." (PMID 23484019, 2013). "In human breast cancers, loss of Wnt-5a protein is associated with poor outcome in part because of an increase in distant metastases, suggesting a suppressive role of WNT5A in breast cancer metastasis." (PMID 23484019, 2013). "In contrast, it was shown that WNT5A is critical for macrophage-induced invasion of breast cancer cell lines." (PMID 23484019, 2013). "A highly invasive mouse breast cancer cell line that expresses low to undetectable levels of endogenous Wnt5a, 4T1, was transduced with lentiviruses that either express human WNT5A (4T1-WNT5A) or the vector alone (4T1-vector)." (PMID 23484019, 2013). "When analyzing patients according to breast cancer subtypes, we found that Wnt-5a was a robust prognostic marker for luminal A tumors (p = 0.04; n = 161) but not for luminal B, HER2+ or triple-negative tumors." (PMID 23990917, 2013). "We believe that WNT‐5A‐modulated Cdc42‐ERK1/2 signaling plays an integral part in restricting breast cancer progression and metastasis." (PMID 23727359, 2013). "Because our results indicated that WNT‐5A comprehensively activates Cdc42 in breast cancer cells, we next performed Trans‐well migration and invasion assays with breast cancer cells in the absence or presence of WNT‐5A." (PMID 23727359, 2013). "Despite all these findings it has also been reported from in vitro experiments that Wnt-5a can promote migration and invasion of breast cancer cell lines." (PMID 23990917, 2013). "To rule out the possibility that the increase in active Cdc42 induced by WNT‐5A is a unique property of MDA‐MB468 breast cancer cells, we employed MDA‐MB231 in our experiments." (PMID 23727359, 2013). "Together these data indicate that apart from an initial increase, WNT‐5A confine ERK1/2 activity in breast cancer cells and that impaired ERK1/2 activity renders breast cancer cells less migratory and invasive." (PMID 23727359, 2013). "Further evidence that MMP9 is an important downstream mediator of WNT‐5A‐regulated breast cancer cells migration comes from experiments in which we utilized active human rMMP9." (PMID 23727359, 2013). "Such a possibility is strengthened by the fact that in the unselected cohorts analysed for Wnt5a protein expression there were few premenopausal breast cancer patients." (PMID 23990917, 2013).